IL17A (interleukin 17A)
Diseases named in the same sentence as IL17A in open-access papers (continued):
Sharing a sentence is not in itself a finding about the gene and the disease.
tumor (continued). "Additionally, immunohistochemical analysis of IL‐17A, E‐cadherin and N‐cadherin on the TMA that included 313 HCC tumour specimens from patients with HCC who underwent surgical resection at EHBH revealed consistent results." (PMID 29689643, 2018). "Our previous study indicated that IL‐17A activated AKT to promote tumour progression; therefore, we investigated whether AKT phosphorylation mediated the effects of IL‐17A on EMT and colonization." (PMID 29689643, 2018). "In the lungs of tumor-bearing mice, it was observed a significant increase in the numbers of CD4+Foxp3+IL-10+ and a significant decrease in ROR-γ+IL-17A+CD4+ T cells T cells in metformin-treated and protected animals, phenotypically similar to Treg and Th17 cells, respectively." (PMID 29899823, 2018). "Moreover, the number of CTCs in the mouse circulation was increased by IL‐17A stimulation, indicating that more HCC cells successfully escape from the primary tumour site and struggle to survive in the bloodstream due to IL‐17A stimulation." (PMID 29689643, 2018). "While the JNK pathway is prevalently viewed as one of the IL-17A-induced signaling pathways, the role of JNK1 and JNK2 isoforms in mediating IL-17/IL-17R-controlled tumor-specific responses has never been investigated." (PMID 28562353, 2017). "Based on these previous findings, we hypothesized that IL-17A may regulate the immune checkpoint molecule PDL1 and that inhibition of IL-17A may elicit an anti-tumor immune response in murine models of ER-negative breast cancer." (PMID 27935862, 2017). "In well-differentiated TSCC, IL-17A was mainly expressed in the basolateral cells around the keratin pearl, while in poorly-differentiated TSCC, it was widely expressed in almost all the tumor cells." (PMID 28035060, 2017). "Opposite from the effect of IFN-γ neutralization, IL-17A neutralization decreased tumor number and load both in WT and SHP2CD4−/− mice, suggesting that IL-17A may counteract the effect of IFN-γ to promote tumor, even though it is overridden by IFN-γ." (PMID 27935860, 2017). "Next, we assessed the expression of IL-17A and PDL1 in tumor tissue samples by IHC." (PMID 27935862, 2017). "Additionally, we established that IL-17A promotes PDL1 expression in human tumor cells, monocytes, and DCs, as well as in mouse tumor cells and macrophages." (PMID 27935862, 2017). "We found that anti-IL-17A Ab injection inhibits PDL1 expression in tumor cells, macrophages, and MDSCs, decreased the number of Treg cells in TILs, and increased the number of IFN-γ-producing CD4+ and CD8+ T cells in TILs in ER-negative tumor-bearing mice." (PMID 27935862, 2017). "IL-17A mRNA was significantly increased in 54 of 76 (71.0%) tumor samples compared with matched nonmalignant tissues (P < 0.01)." (PMID 28035060, 2017). "Therefore, we further analyzed the percentages of IL-17A-, IL-6-, IFN-γ-, IL-4-, granulocyte macrophage colony stimulating factor (GM-CSF)- and IL-1β-producing cells in tumor-infiltrating cell populations from mice administered L-4F or Sc-4F." (PMID 29245934, 2017). "Recent studies showed that blocked or genetically-induced absence of IL-17A resulted in significantly attenuated tumor burden in ApcMin/+ mice infected with enterotoxigenic Bacteroides fragilis and in the standard ApcMin/+ model." (PMID 28492497, 2017). "The strong IL-17A and PDL1 expression in ER-negative tumor tissues prompted us to further investigate whether there was a positive correlation between IL-17A and PDL1 expression." (PMID 27935862, 2017). "We speculate that combined IL-17A and PDL1 Abs may enhance the anti-tumor immune response against PDL1 Ab by decreasing PDL1 expression." (PMID 27935862, 2017). "Furthermore, IL-17A serum levels were elevated in CRC patients compared with healthy individuals, positively correlated with tumor size or circulating tumor cells, and predicted poor survival." (PMID 27148488, 2016).
tumor (continued). "In human colorectal cancer, accumulation and expansion of peripheral MN-MDSCs were promoted by an increase of IL-17A, which was mainly secreted by tumor-infiltrating γδT cells rather than Th17 cells." (PMID 27007054, 2016). "In the 4 T1-tumor bearing SKG mice, data demonstrates a significant reduction in the percent of mice that develop bone and lung metastasis when treated with anti-IL17A antibody compared to control mice (80-90% of control mice develop metastasis versus only 40-50% of treated mice develop metastasis)." (PMID 24674692, 2014). "Although, the role of IL-17 in cancer has not been fully studied, the clinical evidence of IL-17A and Th17 cells as pro-tumor factors in HCC have recently been reported." (PMID 25181290, 2014). "To reconfirm that anti-IL-17A treatment indeed reduces the level of SDF-1 in the arthritic mice prior to the development of tumor, we treated non-tumor bearing arthritic mice (C57BL/6 mice injected with CII) with the anti-IL-17A antibody." (PMID 24674692, 2014). "Suppression of IL-17A at tumor sites led to a Th1-dominant environment, and moreover, eliminated myeloid-derived suppressor cells and regulatory T cells at tumor sites but not in splenocytes." (PMID 23372655, 2013). "IL-17A up-regulates production of a variety of proangiogenic factors in vitro, such as VEGF, prostaglandin E1 and E2, and macrophage inflammatory protein-2, by fibroblasts as well as tumor cells." (PMID 23372655, 2013). "In our study, inhibiting of IL-17A at tumor sites decreased tumor- infiltrating Treg cells in MC38 subcutaneous model, but not in B16 subcutaneous model." (PMID 23372655, 2013). "Cytokines such as interleukin (IL)-6, IL-17A, IL-21 and tumor necrosis factor (TNF)-α contribute to the formation of a tumor-supportive microenvironment, while interferon (IFN)-γ is supposed to exert tumor-suppressive functions." (PMID 23109839, 2012). "In contrast to that, most of the cytokines which are assumed to promote tumor development are anti-inflammatory cytokines, as for example IL-10 or TGF-β, indicating that IL-17A might be important for tumor rejection." (PMID 22855687, 2012). "In 22 HCC cases with metastasis, the frequency of IL-17A-positive cells was significantly higher (P = 0.001, paired-samples T test) in tumor tissue (mean: 516±182) than that in adjacent non-tumorous tissues (mean: 164±31)." (PMID 21760911, 2011). "Compared with paired non-tumor tissue, higher frequency of IL-17A-positive cells was detected in tumor tissues in HCCs with metastasis, and the frequency of IL-17A-positive cells was also significantly associated with poor prognosis of HCC (P = 0.01)." (PMID 21760911, 2011). "PCR signal for IL-17A was low in two samples and negative in an additional two samples of tumor adjacent lung tissue." (PMID 21949768, 2011). "Functional study showed that IL-17A could enhance the migration and invasion abilities of HCC tumor cells." (PMID 21760911, 2011). "Notably, HDM-driven tumor promotion was abolished in Il17a -/- but not Il1b -/- mice, identifying IL-17A as a critical mediator." (PMID 41040138, 2025). "NK cells, as well as neutrophils, are more abundant in tumours in the absence of IL17A, but especially the huge antibody production induced by the ENO1 vaccine could be responsible for the antibody‐dependent cytotoxicity against tumour cells." (PMID 40831074, 2025). "At week 12, IL-17A levels were significantly higher in the FMT-CRC group compared to the positive control, reinforcing the hypothesis that CRC-derived microbiota contributes to a pro-inflammatory tumor microenvironment." (PMID 41614846, 2025). "Regarding the cytokine profile, notable modulations were observed in the levels of IL-1β, IL-4, IL-6, IL-10, IL-17A, and TNF-α, particularly in the FMT groups, indicating an influence on the local immune response that could contribute to shaping the tumor microenvironment." (PMID 41614846, 2025).
tumor (continued). "Immunologically, P. micra skews mucosal immunity toward a Th17 phenotype: colonic IL-17A, IL-22, and IL-23 increase, Th17 infiltration rises, and chemokine networks (including CCL20 and several CXCLs) are induced, reinforcing an inflammatory, tumor-supportive microenvironment." (PMID 41007823, 2025). "Studies have shown that IL-17A can promote ESCC tumor cells to produce more chemokines CCL2, CCL20, and CXCL13, enhance B cell migration, or enhance IgG-mediated antibody and complement-mediated cytotoxicity of B cells to tumor cells to inhibit tumor development." (PMID 39906741, 2024). "First, we confirmed that CD4+ T cells in transplanted B16-3340 tumors or the tumor-draining lymph node (TdLN) do not produce IL-17A, unlike cells from the small intestine, by using IL-17A-GFP reporter mice colonized with SFB and treated with anti-PD-1 antibody." (PMID 39185202, 2024). "Subsequent protein-protein interaction network and functional enrichment analyses further revealed that IL-17A might exert its anti-LUAD effects by inhibiting oxidative stress, inflammatory responses, and tumor-related signaling pathways involving ferulic acid 4-sulfate-related genes." (PMID 39257908, 2024). "Moreover, HIS treatment reversed the elevated serum levels of inflammatory factors (IL-6 and IL-17A), stress hormones (NE and COR), and 5-HT, all of which have been shown to be upregulated under chronic stress and promote tumor progression, consistent with previous research." (PMID 39720595, 2024). "Our study found a significant decrease in IL-6, IL-1β, IL-17A, and TNF-α levels in mice after L.p CMU-Pb-L5 intervention, indicating that L.p CMU-Pb-L5 intervention could reduce inflammatory cytokine levels in vivo and slow CRC tumor growth." (PMID 39439459, 2024). "IL-17A is produced mainly by Th17 cells, in addition to IL-17+CD8+ T cells(Tc17), γδT cells, natural killer cells (NK cells), neutrophil, and innate lymphoid-like cells can also secret IL-17A, which play an important role in inflammatory diseases and in the tumor environment." (PMID 39676857, 2024). "First, factors such as Interleukin-17A (IL-17A), granulocyte–macrophage colony-stimulating factor (GM-CSF), granulocyte colony-stimulating factor (G-CSF) and tumor necrosis factor-alpha (TNF-α) from the tumor site enter the blood and then stimulate bone marrow production." (PMID 38609997, 2024). "Therefore, we assumed that IL-17a stimulation leads to the upregulation of FAP expression, activation of stellate cells, and promotion of the growth and proliferation of HCC cells in the tumor microenvironment." (PMID 38740736, 2024). "Unlike in BMDMs, IL-17A did not induce Cd274 upregulation in tumor cells." (PMID 36239683, 2023). "Furthermore, we found a negative correlation between tumor size and serum IL-17A levels, with especially large aggressive tumors (≥800 mm3) having significantly lower IL-17A concentrations (P = 0.0155)." (PMID 37525015, 2023). "Indeed, in the GSE51401 dataset, ICAM1 transcription level was negatively correlated with IL-17A level of tumor tissues and with IL17RC in TECs but not in NECs." (PMID 37605139, 2023). "In summary, IL-17A promotes the proliferation, migration, and invasion of NSCLC cells and the occurrence of EMT, all of which are biological functions that may accelerate tumor progression." (PMID 37978543, 2023). "Although these results could not explain directly the role of IL-17A+ inflammatory cells in tumor development, increased GC development in MNU and H. pylori-treated mice was associated with an elevated number of CD4+ and CD8+ cells." (PMID 36125689, 2023). "For example, Fusobacterium nucleatum was related to IL-17A-related inflammation in human CRC, and Peptostreptococcus anaerobius was described to induce a proinflammatory response in the tumor stroma, contributing to tumor progression via the recruitment of tumor-infiltrating immune cells." (PMID 36983053, 2023).
tumor (continued). "Moreover, IL-17A-mediated mitochondrial dysfunction induces ROS-induced activation of the NLRP3 inflammasome and cleavage of caspase-1, driving pyroptosis and eventually promoting CD8 + T-cell infiltration into the tumour microenvironment." (PMID 37211606, 2023). "G-CSF and IL-17A serum levels were greater in tumour-bearing mice than in normal mice." (PMID 37162544, 2023). "However, immunoreactivity for IL-17A was observed mainly in cytoplasm of intratumoral inflammatory cells but not tumor cells." (PMID 36125689, 2023). "However, since we only analyzed the IL-17A mRNA levels, and not the expression and localization of IL-17A protein, we cannot distinguish the function of tumor and stroma-induced IL-17." (PMID 36098359, 2022). "Interestingly, during tumour development, CD4+T cells may progressively transdifferentiate into IL-17A+ FOXP3+ and ex-Th17 IL-17A- FOXP3+ T cells." (PMID 36569832, 2022). "Ddx5 was increased in the whole skin lesions of MC903- or IMQ-treated Cd93–/– mice compared with their wild-type counterparts, along with fewer plaques on the ears or dorsal skin and reduced expression of Il4, Il13, Ccl11, Ccl17 and Ccl22 or Cxcl1, Cxcl2, Ccl20, Il23, Il17a and Il36γ." (PMID 36271146, 2022). "The control + IL-17A group and the CTSK siRNA + IL-17A group showed higher expression of CTSK compared to the other two groups; therefore, we conducted flow cytometry on the tumor tissues of the four groups of nude mice to observe the immune cells infiltration." (PMID 36138018, 2022). "Moreover, both PN and IL17A increase WNT3A secretion indicating that WNT3A signaling may have a crucial role in tumor cellular hierarchy." (PMID 35982950, 2022). "However, the mechanism underlying immune cells infiltration in Lewis lung carcinoma (LLC) tumor tissues mediated by RORγt agonist or IL-17A is not fully understood." (PMID 35459193, 2022). "Thus, this polyfunctional population of Teff cells, which produce IFNγ and IL-17A and express MDR1, CD161, and CD73, may be an interesting therapeutic target for modulating their proinflammatory properties in the tumor context." (PMID 36297616, 2022). "While Th2 and Th17 cells may promote tumor growth through expression of immunosuppressive cytokines including IL-4, IL-5, IL-13, and IL-17A, although the contribution of these cells to the tumor immune landscape is not completely clear." (PMID 34202979, 2021). "Notably, differing IL-17A and IL-8 levels were shown by some studies to not affect patient prognosis, despite evidence suggesting multiple pro-tumour pathways upregulated by these cytokines in GC." (PMID 34944729, 2021). "In conclusion, the unique metabolic phenotype displayed by macrophages in the absence of IL17A suggests their ability to recruit more effector T-cells into the tumor area, and also potentially create an inflammatory microenvironment for antigen-presenting cells that take-up dying tumor cells." (PMID 33802061, 2021). "However, the role of TGF-β for the emergence of IL-17A+IL-22-, IL-17A+IL-22+, and IL-17-IL-22+ CD4+ T cells in the tumor microenvironment remained unknown and was addressed by our study." (PMID 32451418, 2020). "The Vγ9Vδ2 T cells are specially adapted for tumor immunity through potent and broad tumor cytotoxicity, MHC-independency, relative resilience to the suppressive role of programmed cell death-1 (PD-1), low IL-17A production, and activation of NK cells cytotoxicity." (PMID 32456316, 2020). "In conjunction with the observation that IL-17A+ TILs are enriched in TNBC patients, it is reasonable to speculate that IL-17A-induced anti-tumor immunity is a potential mechanism that works synergistically with neoadjuvant chemotherapy to achieve a favorable clinical response." (PMID 32770025, 2020). "Since IL-17A may also be produced by neutrophils, we did rule out a decrease in granulocytes in the tumor by testing for GSR expression, which was unchanged." (PMID 33042110, 2020).
tumor (continued). "Since IL-17A has not been directly administered in biologically relevant concentrations in GI tumors, we performed this experiment and found it was effective in reducing tumor growth, concurrent with supporting a cytotoxic immune response." (PMID 33042110, 2020). "In our NASH-HCC model, an aggressive growth pattern of tumor nodules was detected in the FGF21KO mice with a single injection of DEN and HFMCD feeding, while HCC lesions, in terms of nodule number and nodule size, was significantly alleviated when the animals were treated with anti-IL-17A antibody." (PMID 32929325, 2020). "Furthermore, on day 23 of B16F10 cell injection, α-GalCer treatment increased the frequency of total NKT cells as well as IFN-γ-producing NKT cells whereas the frequency of IL-4 or IL-17A-producing NKT cells were not affected in the tumor (data not shown)." (PMID 31387637, 2019). "The tumor-infiltrating lymphocytes (TILs) in the WT → WT mice demonstrated an enhanced percentage of IL-9-producing CD4+ T cells but no increased percentages of IFN-γ- or IL-17A-producing CD4+ T cells or Tregs." (PMID 31266950, 2019). "The observation that treatment with SLN-TMZ increases expression of IL-17A without affecting expression of IL-10 suggests that this treatment may also exert positive effects on the anti-tumor immune response by increasing the TH17/Treg cell ratio." (PMID 29364157, 2018). "While IL-17AnegFoxp3neg and IL-17AnegFoxp3+ Treg cells do not affect tumour progression when compared with control tumour-bearing mice, both subsets of IL-17A-producing Foxp3+ and Foxp3neg cells enhance tumour progression compared with IL-17AnegFoxp3+ Treg cells." (PMID 28290453, 2017). "Notably, while IL-17A is reported to induce neoplastic transformation and proliferation of some tumor cell lines in vitro, it fails to do so in many other tumor cell lines." (PMID 28562353, 2017). "In addition, IL-17A triggers STAT3 activation in tumor cells, thereby favoring tumor growth." (PMID 27832300, 2017). "To address whether targeting of IL-17A could affect PDL1 expression in tumor tissues, we prepared single tumor cells from tumor-bearing mice treated with anti-IL-17A Ab and gated the tumor cells and live TILs to check PDL1 expression on tumor cells, macrophages, and MDSCs." (PMID 27935862, 2017). "In the presence of tumor, γδ T cells, rather than Th17 cells, were predominant source of IL-17A." (PMID 28432279, 2017). "We demonstrated that targeting of IL-17A (200 mg/mouse) suppressed tumor growth but could not prolong the survival time of tumor-bearing mice." (PMID 27935862, 2017). "However, following stimulation with α-c-myc tag monoclonal antibody or the tumor cells 24JKERB, we detected a range of cytokines, including IL-4, IL-2, IL-17A, TNF-α, IL-6 and IFN-γ from CAR T cells, while no significant response was observed from WT T cells." (PMID 27153556, 2016). "TGF-β and IL-17A expression levels were not significantly different between kCYC and WT mice, suggesting that overall decreased cytokine expression was specific to tumor immune responses." (PMID 26098776, 2015). "Thus, our results argue that the control of tumor multiplicity by Tregs requires both the absence of IL-17A and a functional thymus." (PMID 26146642, 2015). "Cyclin E proteolysis might be a tumor specific mechanism as IL-17A failed to up-regulate the generation of LMW-E forms in the non-transformed mammary epithelial MCF10A cells although these cells express significant levels of IL-17RA and IL-17RC." (PMID 26154409, 2015). "In the studies using IL-17−/− mice, the role of systemic IL-17A could be evaluated on tumor progression and, however, the role of local IL-17A on tumor progression could not to be understood." (PMID 23372655, 2013). "However, the role of Th17 cell on tumor growth remains to be clarified because in the present study we focused on the effect of local IL-17A on tumor growth but not on the function of Th17 cells." (PMID 23372655, 2013).